ANXA1 (annexin A1)
Diseases named in the same sentence as ANXA1 in open-access papers (continued):
Sharing a sentence is not in itself a finding about the gene and the disease.
nephritis (2 papers, 2022 to 2026). Inflammation of renal tissue. "Glomeruli from WT and AnxA1-deficient mice frequently showed segmental or global fibrinoid necrosis along with the formation of tip lesions at d5 after nephritis induction." (PMID 36311242, 2022). "Using an unbiased state-of-the-art lipidomics approach, we found markedly elevated levels of PGE2 and its predominant metabolite 15-keto-PGE2 in the kidney homogenates of the AnxA1-deficient mice at d10 after nephritis induction." (PMID 36311242, 2022). "Quantification of positive cells at d10 after nephritis induction showed a significant 7-fold increase in WT (713 ± 52%, p < 0.01) and a 3.8-fold increase in AnxA1-deficient mice (387 ± 32%, p < 0.01) relative to the respective control animals." (PMID 36311242, 2022). "Analysis of GR1+ neutrophils revealed a numerical increase at d5 and a significant 9-fold increase at d10 after nephritis induction in AnxA1-deficient mice as compared to the AnxA1-deficient controls (8,804 ± 1,481%, p < 0.01)." (PMID 36311242, 2022). "Renal CD19+ B-lymphocytes showed a marked, 5-fold increase (529 ± 160%, p < 0.01) in the AnxA1-deficient mice at d10 after nephritis induction, despite inter-animal variations, as compared to AnxA1-deficient control mice." (PMID 36311242, 2022). "In conclusion, we have shown that AnxA1-deficient mice show a severely aggravated course of nephrotoxic serum nephritis with increased glomerular and tubulointerstitial damage as well as proteinuria." (PMID 36311242, 2022). "At d10 after nephritis induction, numbers of immunoreactive cells were further increased in the wildtype mice and more dramatically in the AnxA1-deficient mice." (PMID 36311242, 2022). "In summary, these results show a marked aggravation of renal damage in the AnxA1-deficient mice 10 days after nephritis induction." (PMID 36311242, 2022). "A central result of our study is the highly increased abundance of neutrophils in the glomeruli and in the tubulointerstitium of AnxA1-deficient mice at d10 after nephritis induction." (PMID 36311242, 2022). "Using the nephrotoxic serum nephritis model of cGN in wildtype (WT) and AnxA1-deficient mice, we here show that AnxA1 protein abundance is increased at d10 after nephritis induction in WT mice." (PMID 36311242, 2022). "In contrast, at d10 after nephritis induction, we observed higher numbers of infiltrating leukocytes along with increased glomerular and tubulointerstitial damage in the AnxA1-deficient mice as compared to the WT controls." (PMID 36311242, 2022). "After nephritis induction, the number of F4/80+ immunoreactive cells showed a numerical increase in both, WT and Anxa1-deficient mice at d5 and a further marked increase at d10." (PMID 36311242, 2022). "In contrast, glomeruli in the AnxA1-deficient mice displayed large accumulations of Ly6G+ cells at d5 and d10 after nephritis induction." (PMID 36311242, 2022). "Renal tissue levels of eicosanoids and related lipid mediators were measured by mass-spectrometry lipidomics analysis in WT and AnxA1-deficient mice at d10 after nephritis induction." (PMID 36311242, 2022). "Quantitative real time RT-PCR revealed a 11.5-fold increase of renal Col1A1 mRNA abundance in WT (1,054 ± 188%, p < 0.01) and a 11.7-fold increase in AnxA1-deficient mice (1,169 ± 113%, p < 0.01) at d10 after nephritis induction." (PMID 36311242, 2022). "At d10 after nephritis induction, quantification of Sirius Red signal demonstrated only a numerical increase in the signal density in WT (165 ± 47%, p = n.s.)and a significant 13-fold increase (1,285 ± 321%, p < 0.01) in AnxA1-deficient mice as compared to the respective controls." (PMID 36311242, 2022). "Single-cell RNA sequencing identified a distinct monocyte-derived Anxa1+Spp1+ macrophage subset that expands during nephritis and displays a profibrotic transcriptional signature." (PMID 41800263, 2026).
nephritis (continued). "Quantification of necrotic glomeruli at d5 after nephritis induction showed significantly increased numbers in nephritic WT (32.2 ± 4.7%, p < 0.01) and AnxA1-deficient mice (31.4 ± 5.4%, p < 0.01) without significant differences between both genotypes." (PMID 36311242, 2022). "To assess the influence of AnxA1 on the renal transcriptome in the setting of nephrotoxic serum nephritis, we performed NGS followed by pathway analysis on WT and AnxA1-deficient mice at d10 after nephritis induction." (PMID 36311242, 2022).
ocular toxoplasmosis (2 papers, 2012 to 2021). Ocular toxoplasmosis is an infection in the eye caused by the parasite, Toxoplasm a gondii. "The higher expression of AnxA1 was also observed in neutrophils in ocular toxoplasmosis in mice and culture of retinal pigmented cells infected with Toxoplasma gondii." (PMID 34831393, 2021). "The aim of this study was to evaluate the expression of the protein annexin A1 (ANXA1), a potent endogenous regulator of the inflammatory process, in ocular toxoplasmosis." (PMID 22740770, 2012). "Positive modulation of endogenous AnxA1 in inflammatory cells in the eyes of mice and retinal pigment epithelial cells (ARPE-19) infected with Toxoplasma gondii suggests the protein can be used as a therapeutic target in ocular toxoplasmosis." (PMID 34831393, 2021). "The positive modulation of endogenous ANXA1 in the inflammatory and RPE cells during T. gondii infection suggests that this protein may serve as a therapeutic target in ocular toxoplasmosis." (PMID 22740770, 2012).
oropharyngeal cancer (2 papers, 2014 to 2025). Carcinoma, predominantly squamous cell, arising from the epithelial cells of the oropharynx. "In relation to oral and oropharyngeal cancer, significant associations were observed for a suite of genes including HSPA5, TNFAIP6, AKR1C1, CASP1, ANXA1, and MYC." (PMID 41023518, 2025). "We have noticed a reduced expression of ANXA1 in oropharyngeal cancer compared to the expression observed in the epithelium of the tumor margin and in the non-neoplastic controls, a finding that is in agreement with the majority of studies focusing on cancers of the head and neck." (PMID 24782913, 2014). "We observed a hypoexpression of ANXA1 and ANXA1-TYR in oropharyngeal cancer." (PMID 24782913, 2014). "The reduction in ANXA1-TYR in oropharyngeal cancer was independent of HPV status, which may reflect the use of the protein by EGFR in the process of inducing cell proliferation independent of whether the etiology of the tumor involves the virus or not." (PMID 24782913, 2014). "We did not observe a relationship between the expression of ANXA1 or its phosphorylated forms and the presence of HPV in oropharyngeal cancer." (PMID 24782913, 2014).
primary immunodeficiency (2 papers, 2020 to 2023). "In terms of our analysis, we found the highest ratio of ANXA1 in the primary immunodeficiency pathway." (PMID 32226026, 2020).
pulmonary arterial hypertension (2 papers, 2018 to 2025). Pulmonary arterial hypertension (PAH) is a group of diseases characterized by mean pulmonary artery pressure >20 mmHg and elevated pulmonary arterial resistance leading to right heart failure. "Annexin A1 was found to interact with CBF/NF-Y during pulmonary hypertension-mediated RV hypertrophy and negatively regulate CBF/NF-Y DNA binding." (PMID 30096794, 2018). "Annexin A1 was found to be also carbonylated in response to pulmonary hypertension in the RV, but not in the LV." (PMID 30096794, 2018). "Further, annexin A1 gets degraded in the RV, but not in the LV, in response to pulmonary hypertension, indicating that the activation of CBF/NF-Y-dependent GATA4 gene transcription is through releasing the negative regulation by annexin A1." (PMID 30096794, 2018).
septic shock (2 papers, 2024 to 2025). Shock caused by infection; frequently caused by gram negative bacteria, although some cases have been caused by other bacteria, viruses, fungi, and protozoa; characterized by fever, chills, tachycardia, tachypnea, and hypotension. "This seemed to portend that ANXA1 may be a protective molecule, whose decline was related to the high mortality in septic shock patients." (PMID 39611143, 2024).
squamous cell carcinoma of penis (2 papers, 2013 to 2014). A squamous cell carcinoma arising from the penis. "This study identified two overexpressed genes, ANXA1 and p16, in penile squamous cell carcinoma positive for high-risk HPVs." (PMID 23341933, 2013). "Overexpression of ANXA1 might be mediated by HPV E6 in penile squamous cell carcinoma of patients with high-risk HPVs, suggesting that this gene plays an important role in penile cancer." (PMID 23341933, 2013). "ANXA1 immunostaining was significantly increased in the cytoplasm of cells from penile squamous cell carcinoma with high-risk HPVs independently of the subtype compared to HPV-negative penile squamous cell carcinoma (p<0.0001, Tukey’s post hoc test)." (PMID 23341933, 2013). "Recently, a study was published evaluating protein and mRNA expression of ANXA1 in relation to the HPV status in patients with squamous cell carcinoma of the penis." (PMID 24782913, 2014). "ANXA1 and p16 were overexpressed in penile squamous cell carcinoma samples compared with the sample reference (P = 0.002 and 0.0001 respectively) and the fold-change values for gene expression were 7.9 and 8450, respectively." (PMID 23341933, 2013). "Overexpression of ANXA1 mRNA and Annexin-I (ANXA1) protein were detected in squamous cell carcinoma of penis." (PMID 23341933, 2013). "Low-risk HPV positive squamous cell carcinoma of penis showed decreased expression of ANXA1 compared to the high-risk HPV tumours (data not shown for low-risk HPV positive samples and they were not included in the statistical analysis due to the small number)." (PMID 23341933, 2013).
status epilepticus (2 papers, 2019 to 2024). Status epilepticus is defined as a continuous seizure lasting more than 30 min, or two or more seizures without full recovery of consciousness between any of them. "In this study, the role of the ANXA1-derived peptide Ac2-26 in an experimental model of status epilepticus (SE) was evaluated." (PMID 30755225, 2019). "Thus, this study evaluates the role of pharmacological treatment with ANXA1-derived peptide Ac2-26 in the pilocarpine-induced status epilepticus (SE) in rats." (PMID 30755225, 2019).
age (1 paper, 2024). A temporal measurement of the time period elapsed since an identifiable point in the life cycle of an organism. "The anti‐inflammatory factor annexin A1 (ANXA1) is shown to participate in several age‐related diseases; however, its function during vascular aging remains unclear." (PMID 38358087, 2024).
Akinesia (1 paper, 2024). Inability to initiate changes in activity or movement and to perform ordinary volitional movements rapidly and easily. "Taken together, these data show that inhibition of Anxa1+ DANs is sufficient to drive early PD-like motor symptoms in movement speed (bradykinesia), movement vigor, and tremor, but not sufficient to cause akinesia." (PMID 39763754, 2024).
alcoholic liver diseases (1 paper, 2012). A disorder caused by damage to the liver parenchyma due to alcohol consumption. "In an alcoholic liver disease (ALD) study, Annexin A1 (Anxa1) was highly expressed after liver injury." (PMID 22811744, 2012).
allergic asthma (1 paper, 2022). A asthma with a basis in a pathological type I hypersensitivity reaction. "In the present study, we evaluated the potential ability of AnxA1 to modulate lung inflammation and remodelling in two distinct models of allergic asthma in mice." (PMID 35269381, 2022). "This study evaluated the effect of endogenous AnxA1 and its N-terminal peptide Acetyl 2-26 (Ac2-26) on allergic asthma triggered by house dust mite (HDM) extract in mice." (PMID 35269381, 2022).
allergic contact dermatitis (1 paper, 2024). An inflammatory skin condition caused by an immune response to direct contact between the skin and an allergen. "Given that pain and itch share many neural mechanisms, we employed two mice models of chronic itch to study the underlying targets and therapeutic potential of ANXA1, comprising allergic contact dermatitis-induced itch and cholestatic itch." (PMID 38790419, 2024). "We described the therapeutic potential of intrathecal and intravenous ANXA1 mimetic peptide Ac2-26 in chronic itching using two mice models of allergic contact dermatitis-induced itch and cholestatic itch in this pre-clinical research." (PMID 38790419, 2024).
amyloidosis (1 paper, 2016). A disorder characterized by the localized or diffuse accumulation of amyloid protein in various anatomic sites. "In the present study, we demonstrate that brains of AD patients and a murine transgenic model of amyloidosis express higher levels of ANXA1, not only in microglia but also in astrocytes and neurons." (PMID 27590054, 2016).
anaplastic astrocytoma (1 paper, 2017). "Significant increases in IGF2R were observed in diffuse and anaplastic astrocytomas and oligodendrogliomas, increased PDCD6IP in diffuse and anaplastic astrocytomas, and increased ANXA1 in anaplastic astrocytomas relative to normal brain." (PMID 27770278, 2017).
aortic stenosis (1 paper, 2022). Aortic valve stenosis is a aortic valve disease caused by the incomplete opening of the aortic valve. "The analysis of the pericardial fluid proteome through a state-of-the-art MS instrument identified annexin A1, annexin A2, and vimentin as potential biomarkers of AF in severe aortic stenosis." (PMID 35207752, 2022). "This study is the first to identify annexin A1 as a marker of AF in aortic stenosis and in the pericardial fluid." (PMID 35207752, 2022). "Annexin A1 could contribute to AF pathophysiology in aortic stenosis and function as a countermeasure of inflammation, thus possibly representing a marker of disease progression." (PMID 35207752, 2022). "Annexin A1 is a novel pericardial fluid biomarker of AF in patients with severe aortic stenosis." (PMID 35207752, 2022).
bile duct cancer (1 paper, 2014). "The mRNA and protein expression profiles of ANXA1 were studied in human esophageal, gastric, pancreatic, colorectal, liver, and bile duct cancers using Real-Time PCR, western blotting, and immunohistochemistry." (PMID 25038797, 2014).
breast adenocarcinoma (1 paper, 2023). "As observed in MCF7 breast adenocarcinoma cells, our data indicate that the absence or reduction of ANXA1 in placental cells might underlie the cell death response and impair placental function." (PMID 37373303, 2023).
candidiasis (1 paper, 2022). Infection with the organism Candida. "Common inflammation-associated oral conditions include lichen planus and candidiasis, but the status of GILZ and Annexin A1 in these human conditions remains to be established." (PMID 35563776, 2022).
cardiac arrest (1 paper, 2019). Cessation of breathing and/or cardiac function. "The aim of this study was to determine the neuroprotective efficacy of a bioactive Annexin A1 short peptide (ANXA1sp) in a small animal model of exsanguination cardiac arrest and EPR." (PMID 31258464, 2019). "This study aims to examine whether systemic administration of an Annexin-A1 bioactive peptide (ANXA1sp) could resolve neuroinflammation and induce sirtuin-3 regulated cytoprotective pathways in a novel rat model of exsanguinating cardiac arrest and EPR." (PMID 31258464, 2019). "Our data provide new evidence that engaging pro-resolving pharmacological strategies such as Annexin-A1 biomimetic peptides can effectively attenuate neuroinflammation and enhance the neuroprotective effects of EPR after exsanguinating cardiac arrest." (PMID 31258464, 2019).
cataract (1 paper, 2025). Partial or complete opacity of the crystalline lens of one or both eyes that decreases visual acuity and eventually results in blindness. "A connexin gene-deficient mouse strain develops cataracts, which become less susceptible to cataractogenesis if they carry a specific ANXA1 variant." (PMID 40649110, 2025).
cervical dysplasia (1 paper, 2008). "We propose that in cervical dysplasia/pre-cancer and invasive cancer, annexin A1 tyrosine phosphorylation leads to its solubilization and subsequent extravasation in serum as evidenced by its presence in tumor microvasculature but not in microvascular environment in controls." (PMID 18637184, 2008).
cervical tumors (1 paper, 2021). "In Wang’s study, ANXA1 was found to be highly expressed in normal cervical squamous tissue, and its expression was significantly reduced as the tissue morphology changed with the progression of cervical tumors." (PMID 34484309, 2021).
cholestasis (1 paper, 2024). Impairment of the bile flow caused by obstruction within the liver, or outside the liver in the bile duct system. "Furthermore, this is the first research in which both spinal (intrathecal) and systemic (intravenous) therapies with ANXA1-derived peptide Ac2-26 have been found to prevent and attenuate persistent itch-like scratching behaviors following ACD and cholestasis." (PMID 38790419, 2024).
chronic cholecystitis (1 paper, 2020). "One of these proteins, ANXA1, is previously reported to be overexpressed in GBC tissue in comparison to peri-tumoral tissue (PTs), adenomatous polyp and chronic cholecystitis (CC)." (PMID 33261560, 2020).
Chronic constipation (1 paper, 2018). Constipation for longer than three months with fewer than 3 bowel movements per week, straining, lumpy or hard stools, and a sensation of anorectal obstruction or incomplete defecation. "Here, we have grafted a tripeptide from the annexin A1 protein into linaclotide, a 14-amino-acid peptide with three disulfide bonds, which is currently in clinical use for patients with chronic constipation or irritable bowel syndrome." (PMID 30301200, 2018).
chronic lung disease (1 paper, 2013). According to the definitions of the American and British Thoracic Societies, including pulmonary functional tests, X-rays, and CT scans for items such as fibrosis, bronchiectasis, bullae, emphysema, nodular or lymphomatous abnormalities. "The combination of CCSP deficiency and altered ANXA1 function attributable to these modifications has been speculated to contribute to the hyperinflammatory state observed in chronic lung diseases, though little is known about the specific impact of these acidic modifications on ANXA1 function." (PMID 24187664, 2013).
chronic prostatitis (1 paper, 2023). An infectious or non-infectious chronic inflammatory process that affects the prostate gland. "Hyaluronic acid (HA)/CD44 regulates Th1 differentiation by activating the Annexin A1-AKT-mTOR signaling pathway, promoting the pathogenesis of chronic prostatitis/chronic pelvic pain syndrome (CP/CPPS)." (PMID 37266437, 2023).
co-infection (1 paper, 2014). "maxima co-infection compared with uninfected controls (ANXA1, HSP90B1, VEGFA, MTTP, TNFSF11B, TCF12, APP, and CXCL14)." (PMID 25504150, 2014).
dental caries (1 paper, 2025). The decay of a tooth, in which it becomes softened, discolored, and/or porous. "Furthermore, CCND1 also demonstrated a significant association with the progression of dental caries (odds ratio = 1.15564, 95% CI 1.05554-1.26523, p = 0.0018), while SLC6A4, CASP3, NR3C1, and ANXA1 were linked to diseases of the pulp and periapical tissues." (PMID 41023518, 2025).
disc degeneration (1 paper, 2025). "Functional validation identified LCN2 as a critical immunomodulator, rescuing inflammatory imbalance via regulating ANXA1/Arginase‐1 expression, thus highlighting its therapeutic potential in degenerative disc disease." (PMID 40570207, 2025). "While ANXA1's protective role in osteolysis has been established, this study is the first to define its functional association with LCN2high MDSCs in the IVDD, thereby reinforcing LCN2‐ANXA1 axis as a mechanistically coherent therapeutic target for disc degeneration." (PMID 40570207, 2025).